CXCR6 (C-X-C motif chemokine receptor 6)
Diseases named in the same sentence as CXCR6 in open-access papers (continued):
Sharing a sentence is not in itself a finding about the gene and the disease.
tumor (continued). "Results demonstrated that CXCR6 had more effective anti‐tumour responses with prolonged tumour rejection occurring in 33.3% of mice, whereas mice treated with CXCR3 or CCR4 had only 16.7%–0% prolonged tumour rejection." (PMID 36495108, 2022). "No reduction in liver surface tumor nodules and liver tumor size were found in CD1d-/- and CXCR6-/- mice after A. muciniphila gavage." (PMID 36531991, 2022). "In contrast, when given prophylactically in a mice model of NASH, anti-PD1 treatment led to an increase in the incidence of NASH induced HCC and in the number and size of tumor nodules, which correlated with increased hepatic PD1+ CXCR6+ CD8+ T cells and TNF+ T cells." (PMID 36311728, 2022). "This is supported by the fact that CXCR6 expression is acquired late and occurs in situ in the tumor, and CXCR6 is highly expressed in tumor-specific T cells that are resident but not by those in circulation." (PMID 34607898, 2021). "In addition, we found a positive association between the gene expression level of CD2, CD3D, CD3E, and CXRC6 and the activated fraction of NK cells present in the tumor (CD2: Rho=0.442, CD3D: Rho=0.460, CD3E: Rho=0.423, and CXCR6: Rho=0.401)." (PMID 34692491, 2021). "In the present study, the expression levels of CCL5, CXCR6 and CD3E exhibited a high correlation with the infiltration levels of CD8+ T cells, and the expression levels in HCC samples were lower than those that in adjacent non-tumor samples." (PMID 34218795, 2021). "Patients were stratified by tumor tissue negative (n=15) and positive (n=40) CXCR6 expression into two groups." (PMID 34345211, 2021). "To investigate whether CXCL16/CXCR6 also modulates cell migration, invasion and proliferation in human GBM, we isolated tumor cells from patient's derived biopsies (GBM 13, 19, 40, 45) and analyzed their expression of CXCL16 and CXCR6 by RT-qPCR." (PMID 30542347, 2018). "MSCs may be recruited into the tumor through FPR2, CCR2, CXCR1, CXCR2, CXCR4, CXCR6, and CX3CR1 depending on the types and locations." (PMID 25110692, 2014). "As for ABCG2, CXCR6+ cells were also undetectable in tumor xenografts by flow cytometry (data not shown)." (PMID 21203549, 2010). "On the other hand, an interesting question is why neither ABCG2+ nor CXCR6+ cells were detected in tumor xenografts." (PMID 21203549, 2010). "Taken together, these results imply that CXCR6+ clonally expanded Tregs in SCC may possess migratory properties and a transcriptional profile indicative of immunoregulatory activity, potentially contributing to the immunosuppressive tumor microenvironment." (PMID 40776410, 2025). "In vivo, SBI-457 reduced tumor burden and blocked sorafenib-driven nuclear accumulation of β-catenin, while in vitro screening revealed enhanced responses in HCC cell lines characterized by high soluble CXCL16 secretion and expression of a higher-molecular-weight CXCR6 isoform." (PMID 41375019, 2025). "For instance, tumor-specific CXCR6 knockout (KO) T cells demonstrate greatly reduced TRM cell retention within ovarian tumors, increasing responses in blood and spleen, but reducing resident memory behavior at the primary tumor and leading to poor tumor control." (PMID 40862776, 2025). "Along the EMT spectrum, tumor cells exhibited progressive downregulation of major histocompatibility complex (MHC) class I and II gene expression, along with decreased infiltration of cytotoxic CD8+ T cells, and reduced expression of key effector and trafficking genes (Gzmb, Ccr5, Cxcr6)." (PMID 41280107, 2025). "Mechanisms responsible for low ILC1 metastasis infiltration may rely on intrinsic expression of retention markers (i.e., CXCR6), which do not allow efficient translocation from liver to tumor and will require further investigation." (PMID 40168086, 2025).
tumor (continued). "While it is challenging to definitively attribute an anti-tumor role to CXCL16-expressing NK cells, they may contribute to the activation of CXCR6+ immune cells, such as invariant NKT cells and intratumoral CD8+ T cells, potentially enhancing their anti-tumor capacity." (PMID 39409924, 2024). "In the ENTPD1/ITGAE double positive (tumor‐reactive, tr) population, local TCR clonal expansion and PD‐1 expression were used to classify the following four clusters of effector T cells (Teff): the TOP2A+ proliferating prTeff, IFNGhigh trTeff, IFNGlow trTeff, and IFNG−/CXCR6+ trTeff (trTeff‐CXCR6)." (PMID 38582099, 2024). "Altogether, putatively tumor-reactive DP CD8+ T cells expressed higher levels of coinhibitory markers, had a higher proliferative capacity, and acquired a unique chemokine receptor expression profile by the upregulation of CCR5 and CXCR6 and downregulation of CXCR3 and CXCR4." (PMID 38335302, 2024). "Strong increases toward the tumor center were observed for CXCR3+CXCR6+ cells (population 13) and CCR5+CXCR3+CXCR6+ CD8+ TRM cells (population 9), concurrent with a decrease in CCR5 single-positive (population 12) as well as CCR2+CCR5+CXCR6+ (population 3) CD8+ TRM cells." (PMID 37448786, 2023). "Notably, the frequency of CXCR6+ trNK cells and CD8+ TRM cells increased toward the tumor center." (PMID 37448786, 2023). "Except for CXCR6, all cytokines/cytokine receptors were shown to operate in the spine, with CX3CL1, CX3CR1, IL10, CCL2, CXCL12, and CXCR4 mediating bone marrow colonization, CXCL5 and TGFβ promoting tumor cell proliferation, and TGFβ additionally driving bone remodeling." (PMID 36835198, 2023). "However, the transitional L3 subset and the CXCR6+CD16+ L4 subset with strong anti-tumor activity were absent in the HCC and peritumor liver tissues." (PMID 35856557, 2022). "Furthermore, it was found that CXCR6‐transduced T cell infiltration had more mobility in the tumour tissue in vivo when compared to control T cells without CXCR6." (PMID 36495108, 2022). "Additionally, the 6 markers (KDR, CXCR6, STAT5A, MPL, NFATC3, and TLR6) we found to be downregulated in our late-recurring tumor samples are also biologically relevant to functional T-cell activity, which helps explain their expression and function in this context." (PMID 36195959, 2022). "However, it remains unclear whether CXCR6 is required for the establishment and/or maintenance of TRM cells in the skin, what role it has in tumor immunity, and whether its role includes chemotaxis and/or adhesion." (PMID 34362825, 2021). "To validate this tumor-retention mechanism, we sorted CXCR6+PD-1+ and IL7R+IL18R1+ precursor populations from the tumors of CD45.1+ congenically marked BALB/c mice and intratumorally transferred equal numbers into a 4T1 tumor growing in the mammary tissue of Rag2KO BALB/c mice." (PMID 33979626, 2021). "Similarly, analysis of endpoint tumors in Mrb-OVA alone treated mice revealed that the endogenous tumor-specific CD8+ T cells (marked by OVA tetramer staining) showed high CXCR6 expression compared with non-specific (OVA tetramer negative) T cells." (PMID 34607898, 2021). "Whether CXCR6 expression is stochastic or how it is regulated in tumor TEff/EM cells is still not clear." (PMID 33979626, 2021). "Indeed, CXCR6 and CXCL16 are upregulated in multiple cancer tissues, including primary and metastatic tissues, and cancer cell lines compared to respective normal ones and their levels increase as tumor malignancy progresses." (PMID 31698786, 2019). "We did not observe CXCR6 expression on cells in the tumor stroma." (PMID 26021984, 2015). "Furthermore, CXCR6− cells did not result in any significant, observable tumour mass, indicating that specific CXCR6+ subpopulation showed a strong self-renewal capability in a xenograft model." (PMID 27429260, 2014).
tumor (continued). "However, CXCR6-expressing cells were more aggressive for tumor formation than ABCG2-expressing cells, suggesting that the subpopulation CXCR6+/ABCG2+ cells may be the most potent MCSCs." (PMID 21203549, 2010). "They emphasized that CXCR6 plays an important role in boosting the effectiveness of programmed cell death protein 1 (anti-PD-1) therapy and suggested that the elevated expression of this receptor is driven by factors within the tumor tissue itself rather than by chemotactic signal." (PMID 40943634, 2025). "Moreover, increased upregulation of tissue retention molecules VLA-1, CXCR6, CD103, and CD44 on lung CD8+ T cells following intranasal infection probably prevents the T cell migration to distal subcutaneous tumour site, thus permitting the uninhibited tumour growth." (PMID 36626205, 2023). "Interestingly, a recent study in mice showed that CXCR6 is highly expressed in intratumoral CD8+ T cells and that these cells are more immunocompetent and could enhance the effect of anti-PD-1 blockade to delay tumor progression." (PMID 36341402, 2022). "Furthermore, CXCR6- cells did not result in any significant, observable tumor mass." (PMID 21203549, 2010). "In the SK-Hep-1-derived xenograft model, the CXCR6 antagonist, SBI-457, modestly reduced tumor burden alone and non-significantly in combination with sorafenib while attenuating sorafenib-induced β-catenin upregulation." (PMID 41375019, 2025). "When focusing on liver resident NK (lrNK) cells, characterized by the co-expression of CXCR6/CD69, we found that non-tumor areas in eHCC contained a higher percentage of lrNK cells, both CD56dim and CD56bright, than in tumor areas." (PMID 40547009, 2025). "Looking into the TME, the OVA-specific CD44+ CXCR6+ CD8+ cells expressed higher levels of PD-1, suggesting a lower immune response; thus, in these mice, the immune system failed to prevent tumor growth." (PMID 38774646, 2024). "A considerable number of CXCR6-GFP cells were recruited to the liver and accumulated around the tumor in both tfRFP-immunized and non-immunized mice." (PMID 36438480, 2022). "Compared with normal control tissues, the expression level of CD3D and CD2 in tumor tissues were not significantly different, while the expression levels of CD3E, CD3G, CCL5, CXCR6 and LCK in tumor tissues were lower than those in normal tissues (P < 0.05)." (PMID 34218795, 2021). "The fact that genetic deletion of either CCR5 or CXCR6 abrogated the therapeutic effect of ICB underscores that the coordinated function of all three receptors on the R6R3R5 subset is non-redundant and essential for a successful anti-tumor response." (PMID 41415437, 2025). "Notably, the expression levels of CD3E, CCL5, CXCR6 and LCK in tumor samples and adjacent non-tumor samples were markedly different, and the results were consistent with the results of the analysis using TCGA." (PMID 34218795, 2021). "FcεRIγ− adaptive CD56dim NK cells, isolated from liver tissue irrespective of non-tumor or tumor origin, displayed a low expression of these tissue-resident markers, whereas CD56bright NK cells obtained from liver tissue expressed higher levels of CD69, CXCR6 and CD49a." (PMID 34199483, 2021). "Interestingly, high intratumoral expression of CXCR6 is not primarily driven by chemotactic gradients involving its ligand CXCL16 but rather is upregulated locally by the tumor microenvironment itself, indicating an intrinsic regulatory mechanism within the tumor milieu." (PMID 41149503, 2025).
cancer (101 papers, 2009 to 2026). A tumor composed of atypical neoplastic, often pleomorphic cells that invade other tissues. "In preclinical models, intranasal administration of a cancer vaccine demonstrated reduced antitumor efficacy in CXCR6-deficient mice compared to wild-type counterparts." (PMID 41149503, 2025). "Deficiency in CXCR6 impairs the efficacy of cancer vaccines and responsiveness to anti-PD-1 treatment in preclinical models." (PMID 41149503, 2025). "To validate the spatial association between Carcinoma 3 cells and CXCR6+ Tregs at the protein level, we performed multiplex immunofluorescence staining on serial sections of SCC." (PMID 40776410, 2025). "Here, in most cancer types, higher CXCR6 expression is associated with better overall survival (12 out of 17 types of cancer), while in only 2 out of 17 with worse overall survival." (PMID 33800554, 2021). "The CXCR6/CXCL16 axis has a rather bad press as its increased activity was shown to be associated with invasion of some cancers and development of cardiometabolic disorders." (PMID 31205472, 2019). "Similarly, we found the CXCL16 → CXCR6 LR pair to be positively associated with the immune response for all 18 cancer types." (PMID 34430923, 2021). "Expression levels of CXCL16 and CXCR6 on cancer cells correlated with poor prognostic features including high-stage and high-grade, and expression also correlated with post-inflammatory changes in the cancer stroma as revealed by loss of alpha-smooth muscle actin." (PMID 19690611, 2009). "Receptor genes in LIHC, LUSC, PRAD, STAD, and THYM exhibited significant subcluster differences, with CCR10, CCR5, and CXCR6 differing in more than 15 cancer types." (PMID 41150760, 2025). "Here we demonstrate that the C–X–C motif chemokine ligand 16 (CXCL16)/C–X–C chemokine receptor type 6 (CXCR6) axis plays a critical role in recruiting TNFR2+ Treg cells to MPE, with cancer-associated fibroblasts serving as the primary source of CXCL16." (PMID 41310104, 2025). "This potential interaction is further supported by spatial proximity between Carcinoma 3 cells and CXCR6+ regulatory T cells, as shown in serial immunofluorescence staining." (PMID 40776410, 2025). "In SCC, we observed increased expression of CXCR6, the receptor for Carcinoma 3's CXCL16, specifically in Tregs." (PMID 40776410, 2025). "A forest plot of overall survival (OS) prognostic analysis across different cancer types using TISCH2 revealed that CXCR6’s predictive value varied among cancers." (PMID 39588301, 2024). "CXCR6+ CD8+ T cells are frequently found in tumors and are associated with improved survival outcomes in cancer patients, as well as enhanced antitumor responses and better efficacy of checkpoint blockade therapies." (PMID 39588301, 2024). "In a preclinical cancer model, CXCR6 expression on infiltrating CD8+ T cells are significantly increased post anti-PD-1 treatment." (PMID 37593098, 2023). "In cancer, CXCR6 was demonstrated to be related to greater cancer cell invasiveness in prostate cancer, while inhibiting proliferation and migration in renal cancer." (PMID 36230570, 2022). "The targeting and amplification of antigen-specific TRM expressing CXCR6 and its potential use as a biomarker of response to immunotherapy opens new perspectives in cancer treatment." (PMID 36311728, 2022). "For this reason, it is postulated to use CXCL16-neutralizing antibody or CXCR6 inhibitors during cancer treatment with docetaxel or cisplatin in order to improve the applied therapies." (PMID 33800554, 2021). "On the other hand, soluble CXCL16 (sCXCL16) is implicated in instigating increased migratory and invasive potential of high CXCR6-expressing cancer cells." (PMID 34298782, 2021). "Up to 20% of all peripheral blood CD8+ T cells express CXCR6 in cancer patients and healthy donors, and CXCR6-mediated recruitment occurs in multiple healthy tissues including the lung and liver." (PMID 33968757, 2021).
cancer (continued). "CXCL16, deemed as a unique chemokine, exists both in transmembrane or soluble forms, and the CXCL16/CXCR6 chemokine axis is recently occupying roles in cancer as regulators of cell proliferation, invasion and metastases." (PMID 30996686, 2019). "The PI3K/PTEN/AKT/mechanistic target of rapamycin (mTOR) signal pathway has been clarified to be involved in the CXCR6/CXCL16 biological axis in the cancer realm." (PMID 30620718, 2019). "CXCR6 was located both in the cytoplasm and cell membrane, and showed strong co-localization with its receptor, CXCR6 in cancer cells and epithelial cells." (PMID 29285224, 2017). "CXCL16 is a ligand of the chemokine receptor CXCR6 involved in regulating cancer invasion and metastasis." (PMID 29242629, 2017). "Although CXCR4 has been well studied, CXCR6 has also emerged as a major chemokine of interest in cancer." (PMID 26799186, 2016). "Collectively, these findings indicate that circulating CCR6 and CXCR6-expressing MAIT cells can be easily attracted into the cancer tissues releasing the corresponding chemokines, such as CCL20 and CXCL16, respectively, in MAC patients." (PMID 27517754, 2016). "The expression of CXCL16 and CXCR6 has been investigated in a variety of human cancers and correlated with both improved and reduced survival." (PMID 26021984, 2015). "CXCL16 was expressed in both stromal and cancer cells, whereas CXCR6 was only expressed in cancer cells." (PMID 26021984, 2015). "Then the enzyme-linked immunosorbent assay (ELISA) and flow cytometry were conducted to examine the functional expression of CXCL16 and CXCR6 in three cancer cell lines." (PMID 24897301, 2014). "The receptor for CXCL16, CXCR6, is expressed by several cell types, most notably memory and activated T cells, cancer cells, and ECs." (PMID 21303517, 2011). "In a recent paper, binding of CXCR6 by the cleaved soluble fragment of its membrane-bound ligand CXCL16 (“sCXCL16”) was shown to enhance the proliferation of carcinoma cell lines." (PMID 21203549, 2010). "We also showed that T cells adjacent to cancer cells express CXCL16/CXCR6, that CXCL16 is produced preferentially by CD4+CXCR6+ T cells, and that CXCL16 can enhance the proliferation of T cells." (PMID 19690611, 2009). "Immunofluorescent staining revealed that both CXCL16 and CXCR6 are expressed on CD3+ cells adjacent to cancer cells." (PMID 19690611, 2009). "Moreover, PFKP-overexpressing cancer cells stimulate cancer-associated fibroblasts (CAFs), which in turn augment CD133+ CSLC formation via the CXCL16/CXCR6 axis, establishing a feedforward loop that reinforces chemoresistance." (PMID 42024199, 2026). "In Head-and-neck and lung tumor models, cancer vaccine immunization can drive local CXCL16 upregulation, CXCR6 expression on TRM precursors, and robust TRM recruitment, while impaired TRM cell seeding was observed in CXCR6-deficient mice." (PMID 40862776, 2025). "Furthermore, CXCR6+ CD8+ T cells have been characterized as more immunocompetent compared to their CXCR6− counterparts, further supporting the potential of targeting this axis to enhance immune responses in cancer immunotherapy." (PMID 41149503, 2025). "Conversely, CXCL16 and IL-15 expressing CCR7+ DCs may recruit and sustain CXCR6+ cytotoxic T cells crucial in cancer immunosurveillance." (PMID 38267413, 2024). "Furthermore, CXCR6 emerges as a pivotal marker for tissue-resident memory (TRM) cells across various cancer types and serves as the receptor for the chemokine CXCL16." (PMID 39835121, 2024). "Research indicates that CXCR6 expression can serve as a marker for T cell differentiation and may act as a cancer biomarker." (PMID 39588301, 2024). "Similar to the pan-cancer analysis, LRP2 mutations had high TMB, MSI and immune cell infiltration in EC and also leaded to high expression of immune-related genes, such as CXCL9, CXCR6, CXCL13, ICOS and immune checkpoint genes (CTLA4 and LAG3)." (PMID 35834061, 2022).